MAP2K7 (mitogen-activated protein kinase kinase 7)
Description:
Dual specificity protein kinase which acts as an essential component of the MAP kinase signal transduction pathway. Essential component of the stress-activated protein kinase/c-Jun N-terminal kinase (SAP/JNK) signaling pathway. With MAP2K4/MKK4, is the one of the only known kinase to directly activate the stress-activated protein kinase/c-Jun N-terminal kinases MAPK8/JNK1, MAPK9/JNK2 and MAPK10/JNK3. MAP2K4/MKK4 and MAP2K7/MKK7 both activate the JNKs by phosphorylation, but they differ in their preference for the phosphorylation site in the Thr-Pro-Tyr motif. MAP2K4/MKK4 shows preference for phosphorylation of the Tyr residue and MAP2K7/MKK7 for the Thr residue. The monophosphorylation of JNKs on the Thr residue is sufficient to increase JNK activity indicating that MAP2K7/MKK7 is important to trigger JNK activity, while the additional phosphorylation of the Tyr residue by MAP2K4/MKK4 ensures optimal JNK activation. Has a specific role in JNK signal transduction pathway activated by pro-inflammatory cytokines. The MKK/JNK signaling pathway is also involved in mitochondrial death signaling pathway, including the release cytochrome c, leading to apoptosis. Part of a non-canonical MAPK signaling pathway, composed of the upstream MAP3K12 kinase and downstream MAP kinases MAPK1/ERK2 and MAPK3/ERK1, that enhances the AP-1-mediated transcription of APP in response to APOE.
Synonyms: MEK 7; SAPKK-4; SAPKK4; JNKK2; MKK7; PRKMK7; MAPKK7; MEK
Tractability: Small molecule: a structure with a bound ligand is known; a high-quality ligand is known; it has a binding pocket of medium quality; it belongs to a druggable protein family. PROTAC: ubiquitination databases record sites on it; its protein half-life has been measured; a small molecule that binds it is known.
Target class: STE protein kinase group; Kinase; Enzyme; Protein Kinase; STE protein kinase STE7 family
Chemical probes: BSJ-04-122 (high quality)
Safety:
Unwanted effects reported when the protein is acted on. In parentheses: how it was acted on, where the effect was seen, and who reports it.
Cognitive disorder (inhibition; central nervous system; source: Brennan et al. (2024))
Melorheostosis (activation; bone; source: Brennan et al. (2024))
schizophrenia (inhibition; central nervous system; source: Brennan et al. (2024))
sensorimotor disorder (inhibition; source: Brennan et al. (2024))
Gene: Protein-coding gene on chromosome 19 (7,903,843 to 7,914,480, forward strand). Ensembl gene ENSG00000076984.
Subcellular location: Nucleus; Cytoplasm
Subcellular location (Human Protein Atlas): Cytosol; Plasma membrane
Pathways (Reactome):
Immune System: FCERI mediated MAPK activation; JNK (c-Jun kinases) phosphorylation and activation mediated by activated human TAK1
Cellular responses to stimuli: Oxidative Stress Induced Senescence
Disease: Uptake and function of anthrax toxins
Gene Ontology:
Molecular function: enzyme binding; magnesium ion binding; MAP kinase kinase activity; mitogen-activated protein kinase binding; protein binding; protein kinase binding; JUN kinase kinase activity; protein phosphatase binding; ATP binding; protein kinase activity; protein serine kinase activity; protein tyrosine kinase activity
Biological process: positive regulation of DNA-templated transcription; positive regulation of ERK1 and ERK2 cascade; positive regulation of telomere maintenance; response to heat; response to osmotic stress; response to tumor necrosis factor; response to UV; stress-activated MAPK cascade; cellular senescence; Fc-epsilon receptor signaling pathway; JNK cascade; signal transduction; positive regulation of MAPK cascade; stress-activated protein kinase signaling cascade
Cellular component: cytoplasm; cytosol; nucleus
Genetic constraint (gnomAD): Loss-of-function variants: 12 observed, 42.87 expected, observed/expected ratio (o/e) 0.28, 90% interval 0.18 to 0.45. The synonymous counts are far from expectation, so gnomAD's model fits this gene poorly and the ratio says little. Missense variants: 415 observed, 571.29 expected, observed/expected ratio (o/e) 0.73, 90% interval 0.67 to 0.79. Synonymous variants: 299 observed, 235 expected, observed/expected ratio (o/e) 1.27, 90% interval 1.16 to 1.4.
Homologues: Orthologues: chimpanzee MAP2K7 (100% identical), rabbit MAP2K7 (99% identical), dog MAP2K7 (99% identical), pig MAP2K7 (99% identical), rat Map2k7 (99% identical), mouse Map2k7 (98% identical), guinea pig MAP2K7 (93% identical), tropical clawed frog map2k7 (85% identical), zebrafish map2k7 (81% identical), Caenorhabditis elegans mek-1 (40% identical). Paralogues in human: MAP2K4 (42% identical), MAP2K2 (33% identical), MAP2K1 (33% identical), MAP2K5 (30% identical), MAP3K4 (22% identical), MAP3K2 (22% identical), MAP3K3 (22% identical), NEK1 (14% identical).
Diseases named in the same sentence as MAP2K7 in open-access papers:
MAP2K7 is named in the same sentence as 259 diseases in open-access papers, as found by Europe PMC text mining. Sharing a sentence is not in itself a finding about the gene and the disease. The quoted sentences say what the papers report.
melanoma (192 papers, 2011 to 2026). A malignant, usually aggressive tumor composed of atypical, neoplastic melanocytes. "In melanoma cells, the elevated genes included MAP2K7, RIOK1, GOPC, KHDC4 and PDPK1, which may be associated with stress/drug resistance, protein synthesis, and the regulation of cellular migration." (PMID 41383633, 2025). "These discoveries have led to the emergence of targeted drug treatment for melanoma such as inhibitors of BRAF, mitogen-activated protein kinase kinase 7 (MAP2K7, also known as MEK), and mitogen-activated protein kinase 1 (MAPK1, also known as ERK)." (PMID 32549786, 2020).
breast cancer (73 papers, 2003 to 2025). A primary or metastatic malignant neoplasm involving the breast. "To validate the effects of MAP2K7 loss in ER+ breast cancer, we engineered multiple MAP2K7 CRISPR/Cas9 knockouts in MCF-7 and T-47D cells (MKK7_1 and MKK7_3) and empty vector pLenti cells." (PMID 40826108, 2025). "Loss-of-function mutations in the JNK signaling pathway (e.g. MAP3K1, MAP2K4, and MAP2K7) are implicated in the etiology of breast cancer." (PMID 29856313, 2018). "Finally, we demonstrated that low expression of MAP2K7 and pJNKT183/Y185 was associated with poor outcomes in early and metastatic ER+ breast cancer patients treated with endocrine therapy and CDK4/6 inhibition." (PMID 40826108, 2025). "We provide the rationale to screen ER+ breast cancers for pJNKT183/Y185 and MAP2K7 expression and caution against the use of JNK inhibitors in this setting." (PMID 40826108, 2025). "Here, we have identified inactivation of JNK signalling, specifically loss of the JNK kinase MAP2K7, as a major determinant of insensitivity to combined endocrine therapy and CDK4/6 inhibition in ER+ breast cancer." (PMID 40826108, 2025). "We developed multiple CRISPR/Cas9 knockout ER+ breast cancer cell lines (MCF-7 and T-47D) to investigate the effects of MAP2K7 and downstream MAPK8 and MAPK9 loss." (PMID 40826108, 2025). "We observed that inactivation of JNK signalling, along with low expression of MAP2K7 and MAPK8, were consistently associated with poor outcome or poor drug response in ER+ breast cancer following various treatment regimes." (PMID 40826108, 2025). "We analysed the effects of different splicing events using the OncoSplicing public database, revealing that the percentage spliced in (PSI) values for KIF13A exon 26 and MAP2K7 exon 2 were higher in normal breast tissue than in breast cancer tissue." (PMID 38725048, 2024). "For example, inactivation of MAP2K7 revealed a tumor suppressor function in two models of epithelial lung carcinomas (KRasG12D) and mammary tumors (NeuT)." (PMID 39717752, 2024). "The frequent mutation of the JNK pathway in human breast cancer (including the genes MAP3K1, MAP2K4, and MAP2K7) implicates reduced JNK signaling in the etiology of mammary carcinoma." (PMID 29856313, 2018). "Given that activation of the JNK signalling cascade regulates apoptotic signalling we initially hypothesised that the pro-apoptotic function of JNK signalling would be diminished following MAP2K7 knockout in the tumour suppressive ER+ breast cancer context." (PMID 40826108, 2025). "Loss of MAP2K7 resulted in a 75–97% reduction in endogenous pJNKT183/Y185 levels in MCF-7 and T-47D cells, indicating that MKK7 mediates a substantial proportion of JNK phosphorylation in proliferating ER+ breast cancer cells." (PMID 40826108, 2025). "Since the JNK cascade is activated in response to a range of stress-inducing stimuli we assessed whether MAP2K7 mediates stress-induced JNK signalling in ER+ breast cancer cells." (PMID 40826108, 2025). "Therefore, MAP2K7 is a probable primary driver of JUN stability via the JNK pathway in ER+ breast cancer." (PMID 40826108, 2025). "This led us to hypothesise that MAP2K7 (MKK7) is a novel and specific determinant of JNK signalling dysfunction in ER+ breast cancer." (PMID 40826108, 2025).
colorectal cancer (41 papers, 2006 to 2025). A primary or metastatic malignant neoplasm that affects the colon or rectum. "Colorectal cancer patients with a higher risk of liver metastases display low levels of miR-493 and elevated MAP2K7 expression." (PMID 34504651, 2021).
lung cancer (40 papers, 2008 to 2025). A malignant neoplasm involving the lung. "In addition, lung cancer patients carrying a rare MAP2K7 p.Glu116Lys variant showed poor prognosis and increased metastases." (PMID 34504651, 2021). "Inactivation of MAP2K7 in KRAS-driven lung cancer accelerates tumorigenesis and reduces survival." (PMID 34616731, 2021).
glioma (27 papers, 2012 to 2026). A benign or malignant brain and spinal cord tumor that arises from glial cells (astrocytes, oligodendrocytes, ependymal cells). "Inhibition of HDAC6 reduces glioma cell proliferation and invasion by destabilizing MAP2K7 protein, decreasing JNK and c-Jun activation, and subsequently downregulating cyclin D1 and matrix metalloproteinases." (PMID 39717752, 2024). "The fact that HDAC4 and MAP2K7 are expressed at high levels suggests that the cancer-promoting effects of MAP2K7 in glioma cells could be stopped using drugs that inhibit HDAC4." (PMID 39717752, 2024). "Furthermore, it was determined through genomic silencing that MAP2K7, not MAP2K4, phosphorylates JNK/c-Jun in glioma cells." (PMID 39717752, 2024).
hepatocellular carcinoma (21 papers, 2014 to 2025). A malignant tumor that arises from hepatocytes. "The TOR signaling pathway regulator-like protein (TIPRL), upregulated in hepatocellular carcinoma cells, inhibits MAP2K7-JNK activation through binding of TIPRL to MAP2K7 and protein phosphatase type 2A (PP2Ac), causing dephosphorylation of MAP2K7 and preventing TRAIL-induced apoptosis." (PMID 39717752, 2024). "Recently, it has been reported that TIPRL is overexpressed in hepatocellular carcinoma, and that knockdown of TIPRL by small interfering RNA causes sustained activation of MKK7 (mitogen-activated protein kinase kinase 7) and JNK (c-Jun N-terminal kinase) by increasing MKK7 phosphorylation." (PMID 32719745, 2020).
colon carcinoma (19 papers, 2007 to 2025). "Notably, the MAP2K7 p.Glu116Lys variant has been associated with lung cancer cell proliferation, tumor growth, and metastasis; however, the link between this variant and colon cancer metastasis remains unclear." (PMID 39717752, 2024). "However, we found that high levels of MAP2K7 protein expression were observed in colon cancer tissue, while moderate expression was observed in normal tissue." (PMID 41515982, 2025). "In addition to leukemia, MAP2K7 inhibition may also benefit cancers associated with increased activation of the MAP2K7-JNK pathway, such as liver metastasis of colon cancer, glioblastoma, and prostate cancer." (PMID 39717752, 2024). "The miR-493 inhibits colon cancer metastasis in the lung by targeting the IGF1R and MAP2K7 transcripts." (PMID 39717752, 2024).
glioblastoma (15 papers, 2015 to 2025). The most malignant astrocytic tumor (WHO grade IV). "Histone deacetylase 6 promoted glioblastoma growth through the MAP2K7/JNK/C-Jun signaling pathway." (PMID 38698487, 2024).
leukemia (15 papers, 2011 to 2025). A malignant (clonal) hematologic disorder, involving hematopoietic stem cells and characterized by the presence of primitive or atypical myeloid or lymphoid cells in the bone marrow and the blood. "Mechanistically, the acceleration of leukemia was linked to the upregulation of the mitogen-activated kinase MAP2K7 because the loss of KLF4 released repression of the Map2k7 gene." (PMID 39717752, 2024). "ATF2 acts as a downstream agent to MAP2K7 alongside c-jun, which increases susceptibility to leukemia." (PMID 37955015, 2023). "Studies have demonstrated that MAP2K7 can regulate tumor cell proliferation, invasion, and metastasis, with activation of related pathways exhibiting anti-leukemia effects." (PMID 40406144, 2025). "The clinical application of potent and specific MAP2K7 inhibitors in leukemia also requires optimal pharmacology and toxicology studies in animal models and pre-clinical evaluation using patient samples." (PMID 39717752, 2024). "Our previous work showed that loss of the pioneer factor KLF4 in a NOTCH1-induced T-ALL mouse model accelerated the development of leukemia through expansion of leukemia-initiating cells and activation of the MAP2K7 pathway." (PMID 34504651, 2021). "The low efficacy observed in in vivo treatment suggests that more research is needed to develop small molecules with increased potency and specificity relative to MAP2K7 and evaluate their capacity to eradicate chemoresistant leukemia-initiating cells in T-ALL patients." (PMID 34504651, 2021). "To evaluate whether inhibition of MAP2K7 with 5Z7O prevents leukemia cells from expanding in vivo, we first treated KOPTK1 cells labeled with firefly luciferase (KOPTK1-Fluc) with 5Z7O or vehicle for three hours and transplanted the same number of viable cells to NSG mice." (PMID 34504651, 2021). "Interestingly, in the T-ALL mouse model, this kinase pathway was also activated in the rare leukemia-initiating cell population, suggesting that inhibition of MAP2K7 could potentially eradicate leukemia-initiating cells responsible for chemoresistance and relapse." (PMID 34504651, 2021). "Although promising results indicated that MAP2K7 inhibition can control leukemia burden in preclinical mouse models, the compounds did not exhibit the desired high potency, high specificity, and low toxicity." (PMID 39717752, 2024). "To evaluate whether the combination of rapamycin and MP could inhibit JNK activation, through reduced MAP2K7 expression, we measured phospho-JNK (p-JNK) and total JNK (pan-JNK) levels in CCRF-CEM human leukemia cell line post-treatment by western blot." (PMID 32776229, 2020).
multiple myeloma (15 papers, 2012 to 2024). "According to the cell line Encyclopedia (CCLE), MAP2K7 is highly expressed in multiple myeloma, chronic myeloid leukemia, lymphomas, B-cell acute lymphoblastic leukemia (B-ALL), and T-cell acute lymphoblastic leukemia (T-ALL)." (PMID 39717752, 2024). "The survival of multiple myeloma (MM) malignant plasma cells is driven through MAP2K7-JNK inhibition by GADD45β activated by constitutively activated NF-κB." (PMID 39717752, 2024). "Further, proteomic analysis revealed higher levels of MAP2K7 expression in acute lymphoblastic leukemia (ALL), lymphoma, and myeloma compared to other cancer types." (PMID 39717752, 2024).
prostate carcinoma (15 papers, 2012 to 2026). A carcinoma that arises from epithelial cells of the prostate gland. "MAP2K7 was identified by NetTar as a target of antineoplastic agents while the protein has been reported to be associated with prostate cancer in TTD." (PMID 26853265, 2016). "For instance, in prostate cancer, DDR1 activates Pyk2 and MKK7 (Mitogen-activated protein kinase kinase 7), resulting in increased expression of the mesenchymal markers vimentin and N-cadherin and decreased expression of the epithelial marker E-cadherin." (PMID 33917302, 2021). "In addition, MAP2K7 also mediates signals from the discoidin domain receptor 1 (DDR1) and promotes the epithelial-mesenchymal transition during prostate cancer metastasis." (PMID 39717752, 2024).
gastric cancer (14 papers, 2012 to 2026). A primary or metastatic malignant neoplasm involving the stomach. "Mitogen-activated protein kinase 7 (MAP2K7) is an important tumor suppressor in gastric cancer, and frequent loss-of-function mutations activate the JNK pathway." (PMID 36439494, 2022). "RT-qPCR analysis and western blot were performed to detect the expressions of PCED1B-AS1 and MAP2K7 in gastric cancer cell lines and tissues." (PMID 38698487, 2024). "The results confirmed that PCED1B-AS1 mediated miR-3681-3p affects the expressions of MAP2K7 in gastric cancer cells(AGS and HGC-27)." (PMID 38698487, 2024). "The results showed that compared with GES-1 cell group, the mRNA expressions of MAP2K7 were significantly up-regulated in gastric cancer cells." (PMID 38698487, 2024). "RT-qPCR results showed that MAP2K7 expression level was negatively correlated with miR-3681-3p expression in gastric cancer tissues." (PMID 38698487, 2024). "Our study found that PCED1B-AS1 negatively regulates miR-3681-3p, promotes the expression of MAP2K7, and exacerbates the malignant progression of gastric cancer." (PMID 38698487, 2024). "In summary, it suggested that PCED1B-AS1 mediated miR-3681-3p/MAP2K7 signaling axis to regulate gastric cancer cell function." (PMID 38698487, 2024). "Firstly, RT-qPCR analysis was used to detect the mRNA expressions of MAP2K7 in different gastric cancer cells." (PMID 38698487, 2024). "Taken together, we confirmed that MAP2K7 is a target of miR-3681-3p in gastric cancer cells." (PMID 38698487, 2024). "MiR-3681-3p mimics or si-MAP2K7 could partly reverse the effect of PCED1B-AS1 on gastric cancer cells." (PMID 38698487, 2024). "Furthermore, knockdown of PCED1B-AS1 could significantly inhibit the invasion, proliferation and migration of gastric cancer cells, which may be related to the regulation of miR-3681-3p/MAP2K7 axis." (PMID 38698487, 2024). "We hypothesized that PCED1B-AS1 mediated MAP2K7 affects the function of gastric cancer cells." (PMID 38698487, 2024). "In conclusion, our study confirmed that silencing lncRNA PCED1B-AS1 directly regulates miR-3681-3p/MAP2K7 signaling axis and inhibited proliferation, invasion and EMT processes of gastric cancer cell lines." (PMID 38698487, 2024). "Our findings showed that MAP2K7, as a downstream target of miR-3681-3p and lncRNA PCED1B-AS1, promoted gastric cancer cell proliferation." (PMID 38698487, 2024). "Interestingly, this study is the first to demonstrate that miR-3681-3p competitively inhibits MAP2K7 expression and inhibits proliferation, invasion, migration and EMT processes in gastric cancer cell lines." (PMID 38698487, 2024). "PCED1B-AS1 accelerated cell proliferation and inhibited cell apoptosis through sponging miR-3681-3p to upregulate MAP2K7 expression in gastric cancer, which indicated PCED1B-AS1/miR-3681-3p/MAP2K7 axis may serve as a potential therapeutic target for gastric cancer." (PMID 38698487, 2024).